PIGR (polymeric immunoglobulin receptor)
Diseases named in the same sentence as PIGR in open-access papers (continued):
Sharing a sentence is not in itself a finding about the gene and the disease.
cancer (62 papers, 1996 to 2025). A tumor composed of atypical neoplastic, often pleomorphic cells that invade other tissues. "Further investigation of the PIGR gene, which has already been studied as a diagnostic and prognostic marker in various cancers of uncertain outcome, should be shifted to advanced tumors and the context of adjuvant therapy." (PMID 40724830, 2025). "The level of PIGR expression varies among cancer types and is associated with different patient outcomes and response to chemotherapy." (PMID 37789066, 2023). "Further studies are required to elucidate the underlying mechanisms linking pIgR expression to cancer." (PMID 33668983, 2021). "PIGR has been described as a putative cancer biomarker in a few studies on various cancers, the majority of which indicate an association between low PIGR expression and more aggressive disease." (PMID 34150619, 2021). "Since a variety of normal non-B cells and malignant cells have also been found to produce immunoglobulins, another interesting avenue of research would be to examine the functional interplay between PIGR and cancer cell-associated immunoglobulins." (PMID 24694107, 2014). "Comparatively few studies have investigated the expression and prognostic significance of pIgR in human cancer, but the majority indicate associations of a high pIgR expression with a more favourable phenotype and an improved survival." (PMID 25397670, 2014). "PIGR has been described as a putative cancer biomarker in a few studies on different cancer forms, the majority of which indicate an association between low PIGR expression and more aggressive disease." (PMID 24694107, 2014). "However, elevated PIGR expression has been reported linked to unfavorable prognoses in several cancers." (PMID 41450825, 2025). "Interestingly, high PIGR expression has also been implicated in several cancer types." (PMID 40565234, 2025). "In the pan-cancer expression analysis, we observed that PIGR expression levels were significantly lower in 8 out of 24 cancer types compared to corresponding normal tissues." (PMID 40386563, 2025). "Expression of PIGR gene was shown to negatively correlate with promoter methylation and cancer prognosis." (PMID 40724830, 2025). "The polymeric immunoglobulin receptor (PIGR) plays an anti-cancer role in various human malignancies." (PMID 40386563, 2025). "Significant differences were observed in protein concentration levels between cancer and inflammatory lesions for S100P, PIGR, C1QBP, TAGLN, and CNN1 (P ═ 0.0006, P ═ 0.0032, P ═ 0.0008, P < 0.0001, P ═ 0.0094, respectively) as shown in." (PMID 39284282, 2024). "There is mixed evidence about the role of PIGR in cancer, but some evidence suggests that PIGR promotes oncogenic AKT activity with downstream effects on GSK3B/β-catenin that are reversed by AKT inhibition." (PMID 38954770, 2024). "In the current study, PIGR expression was significantly correlated with the clinical phenotype (cancer vs inflammatory lesions; P ═ 0.0006) and AFP (P ═ 0.045)." (PMID 39284282, 2024). "Polymeric immunoglobulin receptor (pIgR) enriched in EVs from HCC cells can promote cancer stemness and aggressiveness by inducing the Akt/ β-catenin axis rather than activating the SMAD2/3 signaling and inducing EMT in HCC cells." (PMID 39227992, 2024). "Conversely, studies have indicated favorable outcomes with PIGR expression in patients with different cancers, such as those affecting the upper gastrointestinal tract, lung, endometrium, ovaries, and breast." (PMID 39202022, 2024). "In contrast, many studies have reported favourable outcomes with PIGR expression in patients with other cancers, including upper gastrointestinal tract, lung, endometrial, ovarian and breast cancer." (PMID 37789066, 2023).
cancer (continued). "The alteration of PIGR expression, either increased or decreased, has been shown in various malignant and premalignant lesions and is related to cancer outcomes." (PMID 36207349, 2022). "We chose LS-513 and LOVO cells for further experiments because they have a higher methylation level in PIGR promoter based on the Cancer Cell Line Encyclopedia database." (PMID 35992840, 2022). "In the two gene clusters, some genes associated with tumorigenesis and cancer progression, such as AGR2, MMP7, LXN, PIGR, and CRABP2, were identified." (PMID 36712886, 2022). "Mechanistically, Smad induced epithelial-mesenchymal transition (EMT) 10 and Rac1/CDC42-MEK/ERK cascade 12 were proved to be potential mechanisms of PIGR related cancer malignancy in HCC." (PMID 33390805, 2021). "In the past decade, modulation of pIgR expression, either elevated or reduced, has been increasingly reported in patients of cancer and metastasis, especially in hepatocellular and pancreatic cases." (PMID 33668983, 2021). "In vivo, PIGR downregulation resulted in reduced cancer cell invasion and diminished stromal activity." (PMID 33390805, 2021). "Other signature genes, including PTN, KLK4, RGMA and PIGR, have also been reported to be involved in cancer progression." (PMID 29642861, 2018). "Our data confirm plasma SAA1, PIGR, SPP24, FASN, and possibly THBS1 as potential biomarkers that are common to different types of malignant tumours and associated with Abnormal Savda." (PMID 25652121, 2015). "Given the important role of pIgR in ensuring the basal to apical transport and secretion of immunoglobulins in a variety of epithelial cells, another interesting avenue of research may be to explore the role of pIgR in the context of the regulation and function of cancer-associated immunoglobulins." (PMID 25397670, 2014). "PIGR expression was significantly higher in intestinal metaplasia (BE or gastric IM) compared to normal tissues and cancer (p < 0.001)." (PMID 24694107, 2014). "The mechanistic basis for the role of pIgR in the carcinogenesis and progression of these heterogeneous cancers, with the common denominator of having a dismal prognosis, merits further study." (PMID 25397670, 2014). "PIGR expression was significantly lower in carcinomas of the serous subtype compared to the mucinous subtype (p = 0.009), and to other subtypes (p = 0.002)." (PMID 24568264, 2014). "On the other hand, polymeric immunoglobulin receptor (PIGR), a protein involved in the trans-epithelial transport of immunoglobulins, is consistently down-regulated in cancer cells." (PMID 23536776, 2013). "Conversely, PIGR expression was significantly higher in 2 cancer types." (PMID 40386563, 2025). "Although PIGR expression was originally thought to be restricted to epithelial cells of the gut, PIGR has also been observed in lung, liver and renal epithelial cells, as well as in cancer cells of different tissue origins." (PMID 40624587, 2025). "Very recently it has been demonstrated that utilizing the tumor‐penetrating abilities of dimeric IgA, intracellular mutated oncodrivers‐specific dimeric IgA antibodies could target and expel the oncoproteins out of PIGR+ cancer cells." (PMID 38522010, 2024). "EVs enriched with pIgR consistently promote cancer stemness and cancerous phenotypes." (PMID 37190239, 2023). "PIGR has been demonstrated and described as a biomarker in many cancers." (PMID 37789066, 2023). "There are 4 genes (UACA, PTTG1IP, PIGR, CD81) of this GO term may interacted with ACTR2, EIF6 and hsa-miR-139-5p at the same time, and they play an important role in cancer associated pathway: apoptotic process (UACA, PTTG1IP) and immunity (PIGR, CD81)." (PMID 37365497, 2023). "Nevertheless, the role of PIGR in cell proliferation varies in other cancer cell types." (PMID 37789066, 2023). "According to our results, we believed that PIGR might simulate ribosome pathway activation and promoted cancer progression." (PMID 33390805, 2021).
cancer (continued). "LINC00261, TNFRSF11A, CASP1, ST6GALNAC1, and PIGR also play prognostic roles in cancer." (PMID 31689990, 2019). "High expression of PIGR has been demonstrated to correlate with an improved patient outcome in several cancer forms including EOC and, speculatively, this may be attributed to a negative regulatory function of PIGR on B-cell TILs, or vice versa." (PMID 27048364, 2016). "One study speculated that overexpression of PIGR may be part of the host’s response to the presence of cancer cells or to carcinogenic stimulus." (PMID 24568264, 2014). "Speculatively, pIgR may interact and modulate levels of cancer-cell derived immunoglobulins in certain malignancies, or subgroups thereof, thereby exerting either promoting or suppressive effects on carcinogenesis." (PMID 25397670, 2014). "The accumulated experimental evidence so far indicates that such atypical immunoglobulins promote growth and proliferation of cancer cells, in turn suggesting that PIGR may regulate these immunoglobulins negatively in the majority of cancer forms, including upper gastrointestinal adenocarcinoma." (PMID 24694107, 2014). "Compared with normal breast tissues, PIGR, GPLD1, PLA2G5 and CORO1A were down-regulated in cancer tissues, while EIF4EBP1 and LPCAT1 were significantly up-regulated." (PMID 41450825, 2025). "Significant differences were observed in the protein concentration levels of S100P, PIGR, C1QBP, TAGLN, and CNN1 between cancer and inflammatory lesions (P ═ 0.0006, P ═ 0.0032, P ═ 0.0008, P < 0.0001, P ═ 0.0094, respectively)." (PMID 39284282, 2024). "Similarly, Galectin-3-binding protein (LG3BP) and polymeric immunoglobulin receptor (PIGR), which were selectively enriched in exosomes isolated from the serum of patients suffering from liver and biliary cancer, could be utilized for diagnosis of cancer." (PMID 39001524, 2024). "In a similar fashion, Polymeric Immunoglobulin Receptor (PIGR) was also found significantly upregulated in CLL cells, as it is in many other types of cancer." (PMID 39202022, 2024). "Correlation analysis further revealed significant associations among these pathways, suggesting estrogen might induce cancer cell apoptosis in CRC, which could account for the sex difference in Epi_PIGR abundance." (PMID 40520886, 2025). "Recent studies suggest that PIGR (and perhaps FCRN) is expressed in several cancer tissues." (PMID 38522010, 2024). "Recurrent mutations in PIGR and ZC3H12A are of particular interest because these have not been described in cancer but have roles in immunoregulation and reflect distinct mechanisms of positive selection in the IBD colon." (PMID 32697969, 2020). "Of the 201 downregulated genes, 125 were identified in the previous study (GEO results) and only 76, such as cysteine rich domain 2 (STAC2), BTNL9, CA4, GPIHBP1 and PIGR, had not been studied on any cancer." (PMID 31182966, 2019). "The expression of PIGR, DEFB1, LTF, CLU, SCGB2A1 and S100A7, while having a positive role in cancer elimination, were either downregulated or not changed in all or some of the BC subtypes." (PMID 38589404, 2024).
infection (47 papers, 2009 to 2025). The state of being infected such as from the introduction of a foreign agent such as serum, vaccine, antigenic substance or organism. "There are some other even more cryptic infection-related effects seen when the secretary antibody system is disabled by loss of the pIgR or exploited for other reasons." (PMID 36618388, 2022). "SIgA is transported across the intestinal epithelium and into the lumen by binding to the polymeric immunoglobulin receptor (pIgR), where it binds to the pathogen and neutralizes its ability to attach to the intestinal epithelium and cause infection." (PMID 32349313, 2020). "It was suggested that the less diversified intestinal microbiota present in pIgR deficient mice was responsible for reduced infection." (PMID 30984170, 2019). "To test the susceptibility to infection of pIgR KO mice following an oral S. Typhimurium challenge, we fasted mice for 4 hours then orally gavaged 109 CFU of S. Typhimurium." (PMID 29856838, 2018). "As in the case of IgA−/− during BCG infection, pIgR−/− mice are also more susceptible to M.tb within the first 3 weeks of infection, mainly due to an increased influx of neutrophils to the site of the infection." (PMID 28424703, 2017). "When CFTR-mutated mice were infected with P.aeruginosa, pIgR expression was upregulated, probably through the IL-17 pathway, indicating that infection could restore and even upregulate the IgA/pIgR system in this disease." (PMID 36936934, 2023). "In this report, we examined intestinal barrier (IB) function and susceptibility to infection of pIgR knockout mice based on the hypothesis that pIgR plays an important role in gut integrity and protection against invasive gut pathogens." (PMID 29856838, 2018). "The mucosal immune system is primarily responsible for preventing infection caused by luminal microorganisms by inhibiting bacterial attachment or invasion, and it has been proposed that pIgR may be necessary for maintaining the basal tone of innate immunity in the intestinal environment." (PMID 24088505, 2013). "On the other hand, pIgR can facilitate the adherence and infection of host cells, such as epithelial and endothelial cells, by microbial pathogens including Streptococcus pneumoniae, Candida albicans, Norovirus and Epstein-Barr virus." (PMID 40642082, 2025). "L. brevis 23017 improved SIgA levels by regulating the level of IL-5, IL-13, pIgR, J-chain and IgA α-chain to enhance the immune function against S. typhimurium C7731 infection." (PMID 38930517, 2024). "When SARS-CoV-2 infects the respiratory tracts and lungs, mucosal immunity is expected to suppress infection establishment through the transcytosis and secretion of dIgA and pIgM across the lung epithelial cells by pIgR, together with other immune mechanisms." (PMID 39066171, 2024). "The upregulation of pIgR expression is an accepted phenomenon in mammals, one that seems to be driven by infection and inflammatory mediators." (PMID 37893915, 2023). "Consistent with this, expression of the polymeric Ig receptor (pIgR) increased following infection, signifying accelerated trafficking of immunoglobulins across the epithelial barrier." (PMID 36742327, 2023). "In our previous study, we found that WSSV utilizes pIgR as a receptor for its infection through an interaction between its envelope protein, VP24." (PMID 36067252, 2022). "The infection of WSSV to the host cells through pIgR initiates with the stimulation of the binding between MjpIgR and WSSV on the induction of MjpIgR oligomerization to tetramers, and then, the signal is transferred to the cell cytoplasm." (PMID 35458473, 2022). "In this study, we found that WSSV infection activated the mTORC1 signaling pathway to promote its replication via pIgR-mediated infection in shrimp." (PMID 36067252, 2022). "Biallelic A144E transmitted C. rodentium to only 4 of 13 cohoused WT mice (30.8%) and PIgR-KO transmitted infection to 2 of 5 (40%) cohoused WT mice." (PMID 34111031, 2021).
infection (continued). "Some pathogens have evolved strategies to utilize or suppress pIgR expression for the benefit of their infection." (PMID 33668983, 2021). "In GEO series, PIGR mRNA was also upregulated by hepatitis virus B, C, D, and E infection (all p < 0.05)." (PMID 33937393, 2021). "The secretory IgA plays a major role in the mucosal anti-infection immunity and is transported by the polymeric immunoglobulin receptor (pIgR)." (PMID 31936476, 2020). "In the current study, we observed enhanced expression of polymeric immunoglobulin receptor (PIGR) during sub-clinical infection and clinical infection." (PMID 32518370, 2020). "IgA and IgG play a major role in mucosal infection immunity; some cytokines or pathogens have also evolved ways to regulate pIgR and FcRn to facilitate infection." (PMID 31936476, 2020). "MNV replication was reduced in specific regions of the intestine upon infection of dysbiotic polymeric immunoglobulin receptor (pIgR)−/− mice." (PMID 31426458, 2019). "The secretory IgA and IgG play major roles in mucosal anti-infection immunity and are obtained primarily through the polymeric immunoglobulin receptor (plgR) and FcRn-mediated transport." (PMID 32038538, 2019). "In order to upregulate pigR expression as early as 0 to 3 h post-infection, exposure of the host cell to immunogenic signals such as LPS or Stx would have to be immediate, prolonged and stable; which is unlikely to occur in the variable intestinal environment." (PMID 31188867, 2019). "Addressing these and other future studies on how pathogens subvert the pIgR/SIg cycle will aid in further dissecting the complex roles of SIg in mucosal defense and infection." (PMID 29751532, 2018). "Given the crucial role of SIg as a microbial scavenger, some pathogens also evolved ways to modulate and utilize pIgR and SIg to facilitate infection." (PMID 29751532, 2018). "Given the critical defensive role of pIgR and SIg, some pathogens have evolved strategies to hijack this system to enhance their own infection." (PMID 29751532, 2018). "Taken together, these examples suggest that some bacterial, viral and fungal pathogens can subvert the protective functions of pIgR and SIg to facilitate their own infections or inhibit their defense response." (PMID 29751532, 2018). "Binding to pIgR aids in attachment and infection of human nasopharyngeal epithelial cells in vitro by reverse transcytosis." (PMID 29751532, 2018). "We will further highlight the role of pIgR/SC and SIg as a microbial scavenger capable of manipulating host immunity, and address pathogen modulation and utilization of pIgR and SIg to facilitate infection." (PMID 29751532, 2018). "For example, bacterial upregulation of pIgR expression during infection was observed during Chlamydia infection in the epithelium of the human reproductive tract." (PMID 29751532, 2018). "Herein, we will present an overview of the pIgR/SIg system and its role during infection with a focus on the importance of pIgR in the gastrointestinal tract." (PMID 29751532, 2018). "In the present study, pIgR KO mice showed decreased bacterial counts in the liver and spleen following oral infection, suggesting a decreased number of bacteria seeding these tissues." (PMID 29856838, 2018). "Polymeric immunoglobulin receptors (pIgR) may enhance mucosal immunity or worsen an infection through transcytosis of polymeric immunoglobulins or infectious pathogens." (PMID 40642082, 2025). "It is unknown to what extent SARS-CoV-2 may assimilate pIgR to promote its infection—for example, whether the viral spike protein shows any affinity for pIgR." (PMID 39066171, 2024). "The receptor pIgR was affected by EM × BE interaction only at day 7 PI in the jejunum where its expression level in BE + EM chickens was intermediate to those of +EM and C chickens, suggesting that BE may have minimal effects on pIgR during EM infection." (PMID 39911480, 2024).